APOE (apolipoprotein E)
Diseases named in the same sentence as APOE in open-access papers (continued):
Sharing a sentence is not in itself a finding about the gene and the disease.
pheochromocytoma (1 paper, 2011). "Interestingly, for human APOE -491A>T mutation, the -491A displayed an increased affinity for human hepatic nuclear proteins, while the -491A showed an opposite trend for rat pheochromocytoma and human SK-N-SH neuroblastoma nuclear proteins." (PMID 21549015, 2011).
Pleural effusion (1 paper, 2025). The presence of an excessive amount of fluid in the pleural cavity. "We also identified pleural effusion predictive gene signatures, including TMPRSS3, MS4A7, NAPSA, and IGFBP2, while liver metastasis predictive markers included WFDC2, HSPB1, COX6C, APOE, and TUBA1A." (PMID 39955556, 2025). "Unlike the mitochondria-associated genes in pleural effusion, BL liver metastases had elevated apolipoprotein genes, such as APOC1, APOA1, and APOE." (PMID 39955556, 2025).
prostatic intraepithelial neoplasias (1 paper, 2014). "It has been shown that the prostatic intraepithelial neoplasias (PINs) adjacent to clinically manifested cancer are positive for ApoE, whereas more distant PINs are not, suggesting the relevance of ApoE as a marker of aggressiveness in human PCa." (PMID 25004451, 2014).
psychosomatic disorders (1 paper, 2020). "*Adjusted associations between the subjects’ psychosomatic disorders (dependent variable) and APOE E4 and E2 were analysed with linear and logistic regression analyses adjusted for age, gender and BMI." (PMID 32646381, 2020). "Therefore, post hoc analyses were performed to rule out if inflammation could confound the associations between the psychosomatic disorders and the APOE alleles." (PMID 32646381, 2020).
rectum adenocarcinoma (1 paper, 2020). An adenocarcinoma arising from the rectum. "The result illustrated that the hub genes, including NRXN1, ANK2, LPHN2, APOE, TLR8, ESR1, and so on, might be critical for rectum adenocarcinoma, and m6A modification could regulate the abnormal expression of these genes." (PMID 33680913, 2020).
retinal ischemia (1 paper, 2022). A ischemic disease that involves the retina. "In addition, these patients are carefully classified based on family history, characterization for ApoE, and cardiovascular risk factors that may influence the development of retinal ischemia." (PMID 35629270, 2022).
rheumatic diseases (1 paper, 2021). "The second limitation was that laboratory information, such as Apolipoprotein E genotyping, inflammatory biomarkers, auto antibodies of rheumatic diseases, and evaluation of disease activity, were not included." (PMID 33711047, 2021).
Salmonella Infections (1 paper, 2009). Infections with bacteria of the genus SALMONELLA. "The differences were caused by the excess of lipoproteins, as hyperlipoproteinemic ApoE−/− mice were also highly resistant to Salmonella infection." (PMID 19156198, 2009).
salmonellosis (1 paper, 2009). Infections with bacteria of the genus salmonella.
Schistosomiasis mansoni (1 paper, 2014). Schistosomiasis caused by Schistosoma mansoni. "Our report is the first to identify a host genetic factor, APOE polymorphism, which influences the extent and nature of plasma lipid changes associated with schistosomiasis mansoni." (PMID 25051269, 2014). "Thus, the aim of our study was to determine whether the different APOE alleles influence plasma lipid levels and lipoprotein profiles in patients with hepatosplenic schistosomiasis mansoni." (PMID 25051269, 2014). "APOE genotype frequencies among patients with hepatosplenic schistosomiasis mansoni and controls." (PMID 25051269, 2014).
seminoma (1 paper, 2023). A radiosensitive malignant germ cell tumor found in the testis (especially undescended), and extragonadal sites (anterior mediastinum and pineal gland). "Moreover, seminoma displayed high expression of genes associated with innate immune response, regulation of B cell activation (e.g., CCL5, APOE, MIF, NOP53), suggesting that the immune activity in TME play a role in tumorigenesis." (PMID 38123589, 2023).
serous carcinomas (1 paper, 2014). "In addition, the overexpression of the human leukocyte antigen-G (HLA-G) system is found in 61% of cases, and there is overexpression of apolipoprotein E (apoE) in 66% of cases, but these are rarely found in low grade serous carcinomas." (PMID 24868556, 2014).
serous carcinomas of ovary (1 paper, 2016). "Expression of APOE has already repeatedly been detected in serous carcinomas of ovary." (PMID 27875990, 2016).
squamous cell carcinoma (1 paper, 2024). A carcinoma arising from squamous epithelial cells. "By monitoring various skin health parameters and analyzing proteasome activity, this study found that the SKH-hr2+ApoE and SKH-hr2 models were the most effective for further research into squamous cell carcinoma." (PMID 39456640, 2024).
Staphylococcus infection (1 paper, 2025). "TAM(C1Q) cells, characterised by robust expression of C1Q and APOE and observed consistently across multiple samples, were significantly enriched in lysosomal pathways, Staphylococcus infection pathways, and complement/coagulation cascades." (PMID 40318012, 2025).
testicular germ cell tumor (1 paper, 2022). A germ cell tumor arising from the testis. "However, there is a significant negative association between cancer-associated fibroblast infiltration levels and the expression level of APOE in testicular germ cell tumors." (PMID 37304007, 2022).
thalassemia (1 paper, 2024). An inherited blood disorder characterized by a decreased synthesis of one of the polypeptide chains that form hemoglobin. "An increased risk of cardiac complications related to the GSTM1 haplotype, the ApoE ε4 allele, and some HLA haplotypes has been reported in patients with thalassemia major." (PMID 39062234, 2024).
tuberculosis (1 paper, 2011). A chronic, recurrent infection caused by the bacterium Mycobacterium tuberculosis. "ApoE deficient mice were markedly more susceptible to tuberculosis, evidenced by 100% mortality within 4 weeks of infection with tuberculosis." (PMID 21772670, 2011).
Urinary incontinence (1 paper, 2013). Loss of the ability to control the urinary bladder leading to involuntary urination. "Compared to never users, incident users were older, more likely to be women, report urinary incontinence and more depressive symptoms, and more likely to have an ApoE ε4 allele." (PMID 23741303, 2013).
urolithiasis (1 paper, 2015). Stone(s) within the urinary tract. "Zhang reported that high levels of triglycerides, high-density lipoproteins, cholesterol and ApoE in the blood were risk factors for developing urolithiasis." (PMID 25452799, 2015). "In conclusion, the occurrence of urolithiasis was found to be associated with ApoE gene polymorphisms, and the E4 allele may be a potential susceptibility factor for urolithiasis." (PMID 25452799, 2015). "The associations between ApoE gene polymorphisms and the occurrence of urolithiasis were analyzed." (PMID 25452799, 2015). "Therefore, the E4 allele of the ApoE gene may be used as a potential indicator in the diagnosis and screening of urolithiasis." (PMID 25452799, 2015). "Three common genotypes of the ApoE gene, E3/3, E3/4 and E4/4, were detected in the urolithiasis patients and control group." (PMID 25452799, 2015).
Varicose veins (1 paper, 2024). Enlarged and tortuous veins. "In a case-control study investigating the signaling pathways related to structural changes in varicose veins, it was found that the expression of APOE genes was down-regulated in varicose veins compared to the control group." (PMID 38540308, 2024).
venous insufficiency disease (1 paper, 2024). "Building on this foundation, the overarching objective of the current study is to investigate the presence of APOE gene variations among individuals with venous insufficiency disease and to validate the potential association between these variations and cardiovascular diseases." (PMID 38540308, 2024). "The primary objective of this study was to examine the potential link between APOE gene variations, specifically the ε4 allele (SNP rs429358) and the ε2 allele (SNP rs7412), and the occurrence of cardiovascular disease in individuals with venous insufficiency disease." (PMID 38540308, 2024).
viral hepatitis (1 paper, 2022). An acute or chronic inflammation of the liver parenchyma caused by viruses. "By contrast, portal inflammation in Mdr2-KO mice, human NAFLD livers and viral hepatitis results in marked formation of the C1q-ApoE complex in portal triads with inflammatory cells." (PMID 36304458, 2022). "However, significant numbers of C1q-ApoE complexes formed in both Mdr2-KO, human viral hepatitis, and NAFLD around portal triads where immune cells had infiltrated the liver." (PMID 36304458, 2022). "C1q-ApoE complexes were abundantly detected in liver parenchyma obtained from NAFLD patients and in liver parenchyma and in portal infiltration sites of viral hepatitis." (PMID 36304458, 2022). "Here, we turned to the liver to examine C1q-ApoE complexes in human B- and C-viral hepatitis and nonalcoholic fatty liver disease (NAFLD)." (PMID 36304458, 2022).
visceral leishmaniasis (1 paper, 2018). A severe form of leishmaniasis characterized by irregular bouts of fever, substantial weight loss, swelling of the spleen and liver, and anemia (which may be serious). "Recently, Carvalho and colleagues found that some components of lipid metabolism had an association with lipoprotein lipase (LPL), apolipoprotein E (ApoE), and PPARα gene polymorphisms and presented the risk markers of visceral leishmaniasis (VL)." (PMID 29875768, 2018).
vitiligo (1 paper, 2024). Generalized well circumscribed patches of leukoderma that are generally distributed over symmetric body locations and is due to autoimmune destruction of melanocytes. "Additionally, apolipoprotein E (APOE) was also reported to be downregulated in progressive as well as stable vitiligo patients compared to healthy controls, with the protein being more downregulated in stable vitiligo than the progressive form." (PMID 38715599, 2024).
vivax malaria (1 paper, 2017). "Analysis of the longitudinal cohort of vivax malaria patients by ELISA indicated reversible alterations (compared to the normal serum levels) in the serum abundances of HP, ApoE and Apo A1 during the acute and remission phases of the infection." (PMID 28667326, 2017).
Xanthelasma (1 paper, 2009). The presence of xanthomata in the skin of the eyelid.
ZIKV infection (1 paper, 2022). "This dose-dependent inhibition indicates that anti-ApoE Abs partially inhibit ZIKV infection in Huh7.5 cells, confirming the presence of ApoE at the surface of ZIKV particles." (PMID 35902969, 2022). "The ApoE and Zika E proteins were both located in the virus-induced membrane rearrangements described for flaviviruses and reported during ZIKV infection, in particular." (PMID 35902969, 2022). "For confirmation of the presence of ApoE on secreted ZIKV particles by a different approach, we performed ZIKV infection neutralization assays on Huh7.5 cells, comparing anti-ApoE Abs with anti-Zika E protein Abs." (PMID 35902969, 2022). "ZIKV infections were performed on both liver and microglia derived cell lines in order to proceed to colocalization analysis and immunoprecipitation assays of ApoE and Zika envelope glycoprotein (Zika E)." (PMID 35902969, 2022). "However, at 10 μg/mL, the percentage of infection was significantly reduced by 60% indicating a neutralizing effect of the anti-ApoE Abs on the ZIKV infection process (p value < 0.0001)." (PMID 35902969, 2022). "ApoE has been shown to play a major role at various stages in the HCV infectious cycle, and intracellular lipid disorders have been reported during ZIKV infection." (PMID 35902969, 2022).
cardiovascular disease (489 papers, 2006 to 2026). "When consuming dietary saturated fats, people carrying the APOE ε4 allele often have higher levels of cholesterol, which places them at a greater risk for cardiovascular disease." (PMID 41567168, 2026). "In fact, subjects with the APOE ε4 allele are found to be much less likely to suffer from cardiovascular disease when they adopt customized dietary interventions that reduce their intake of cholesterol and saturated fat." (PMID 41567168, 2026). "The APOE gene plays an important role in lipoprotein metabolism and is associated with the risk of cardiovascular disease." (PMID 41234028, 2025). "Elevated homocysteine levels, a risk factor for cardiovascular disease, have been observed in individuals carrying the APOE ε4 allele." (PMID 41035826, 2025). "The apolipoprotein E (APOE) gene modulates susceptibility to cardiovascular disease, but how exercise and diet interact with APOE genotype remains insufficiently understood." (PMID 41417779, 2025). "Further, the results provide a preliminary atlas of inter-omic associations useful for possible interventions to offset APOE-associated risk in the prodromal stages of AD and cardiovascular disease and to extend healthspan." (PMID 40323280, 2025). "Apolipoprotein E (APOE), as a lipoprotein, is involved in the transport and metabolism of cholesterol and is closely associated with the development of cardiovascular diseases and neurodegenerative diseases." (PMID 41369357, 2025). "Our analysis identified 24 proteins associated with missense variants in various genes, including 11 linked to APOE, a key gene in Alzheimer’s and cardiovascular disease." (PMID 39972214, 2025). "APOE is involved in the clearance of lipoproteins and the regulation of cholesterol homeostasis, processes that are closely linked to cardiovascular disease progression." (PMID 40142959, 2025). "The APOE gene, known for its role in lipid metabolism and cardiovascular disease risk, showed a minor allele frequency of 7.8% in the Kazakh population, which is not significantly different from frequencies in European and East Asian populations." (PMID 41234028, 2025). "Preclinical evidence has shown significant upregulation of ICAM-1 at atherosclerotic-prone sites in murine models of cardiovascular disease that are homozygous apolipoprotein E-deficient (ApoE−/−), particularly within the aorta." (PMID 40630903, 2025). "APOE variants have been widely linked to plasma cholesterol and triglyceride levels, highlighting its importance in determining susceptibility to cardiovascular diseases." (PMID 41007833, 2025). "This SNP is situated about 14 kb from the SNPs that define APOE status, a gene whose variants are well-established for impacting the risk of Alzheimer’s and cardiovascular disease." (PMID 40722932, 2025). "Yet, as conditions for our species continued to improve, diets and lifespan changed, thus rendering ApoE-Є4 susceptible to cardiovascular disease (CVD) and more pronounced effects in women." (PMID 39286457, 2024). "This study examined the association between APOE alleles and cardiovascular disease (CVD) risk, focusing on the ε2 and ε4 alleles." (PMID 38540308, 2024). "Elevated plasma levels of APOE have been linked to increased risks of mortality from all causes, cardiovascular disease, and cancer." (PMID 38956564, 2024). "The APOE gene, which is involved in cholesterol metabolism, has also been linked to both cardiovascular diseases and AD, although the exact mechanism by which it affects these conditions is unclear." (PMID 38489178, 2024). "APOE ε4 has pleiotropic effects on cardiovascular disease and mortality, which are also associated with being male." (PMID 38889280, 2024). "Among these genetic elements associated with cardiovascular diseases, the APOE gene has garnered substantial attention due to its associations with various health conditions." (PMID 38540308, 2024).